PRL (prolactin)
Diseases named in the same sentence as PRL in open-access papers (continued):
Sharing a sentence is not in itself a finding about the gene and the disease.
breast cancer (continued). "Despite their widespread use, there have long been concerns that SSRIs may promote breast cancer by increasing prolactin levels, an accepted risk factor for tumour progression." (PMID 29351761, 2018). "In addition, considerable evidence supports an association of circulating estrogens, androgens, and prolactin with postmenopausal breast cancer risk." (PMID 30180161, 2018). "Additionally, elevated levels of prolactin, a hormone involved in normal breast development and lactation, is associated with a slight increase in breast cancer risk in both pre and postmenopausal women and is important in the etiology of breast cancer." (PMID 29732012, 2018). "However, activation of STAT5, the primary physiological effector of prolactin (PRL), is associated with favorable clinical outcomes, and reduces invasion of breast cancer cells in vitro." (PMID 28103936, 2017). "Consequently, although the association between plasma prolactin levels and risk of breast cancer has been extensively interrogated by many independent studies, it remains to be definitively determined." (PMID 27184120, 2016). "Elevated serum levels of PRL at pregnancy may explain in part the increase in breast cancer risk that occurs over the short-term post-pregnancy." (PMID 27782069, 2016). "However, after removing these two studies, the positive relationship between plasma prolactin levels and risk of breast cancer was still identified, which indicated statistical stability and reliability of our results." (PMID 27184120, 2016). "Therefore, there are reproducible associations, in humans, of increased breast cancer risk, progression, metastases and treatment resistance with increased PRL and the PRLR." (PMID 27782069, 2016). "Combined together, these results indicated that measurement of plasma prolactin levels during the postmenopausal period may be more important and accurate in predicting the risk of breast cancer than during the premenopausal period." (PMID 27184120, 2016). "The increased risk of breast cancer in nulliparous women could be attributed to the high levels of prolactin and circulating oestradiol than in parous and/or older women." (PMID 27760178, 2016). "Furthermore, elevated circulating PRL levels have been positively correlated with breast cancer metastasis and PRLR-deficient mice have prevention of neoplasia progression into invasive carcinoma." (PMID 27542844, 2016). "Our observations further supported that, in addition to its utility as a biomarker, prolactin may also be a risk factor for breast cancer." (PMID 27184120, 2016). "Evidence is also emerging that drugs resulting in elevated prolactin (for example, neuroleptic and hormonal medications) may increase breast cancer risk." (PMID 25887963, 2015). "Several levels of evidence suggest that PRL may be directly associated with effects on ECM in the context of breast cancer." (PMID 26733941, 2015). "Plasma levels of PRL seem to represent a risk factor for breast cancer metastasis." (PMID 26733941, 2015). "This raised the possibility that elevated circulating levels of prolactin could be a risk factor for breast cancer." (PMID 24762632, 2014). "Identifying the mechanisms that underlie the regulation of LKB1 expression in different breast cancer cells may provide new insights into how this protein responds to different stimuli, including PRL or other cytokines such as IL-6." (PMID 24913037, 2014). "PRL has been definitively associated with the onset and progression of human breast cancer by increasing cell proliferation, and may contribute to metastasis by inducing the motility of human breast cancer cells." (PMID 24913037, 2014). "Thus, a direct correlation between serum PRL levels and susceptibility of various rat strains to induction of mammary tumors by chemical carcinogens has been suggested." (PMID 25136563, 2014).
breast cancer (continued). "Finally, a gene signature based on PRL-upregulated genes was associated with prolonged relapse-free and metastasis-free survival in breast cancer patients." (PMID 23758962, 2013). "Furthermore, alternative mechanisms likely lead to loss of Nuc-pYStat5 in human breast cancer, such as inhibition of prolactin-Stat5 signaling by the tyrosine phosphatase PTP1B through inhibition of the Jak2 tyrosine kinase." (PMID 24004716, 2013). "The protein encoded by one of the PRL-regulated transcripts, PTHrP, was examined in a panel of 92 human breast cancers and found by in situ quantitative immunofluorescence analysis to be highly positively correlated with nuclear localized and tyrosine phosphorylated Stat5." (PMID 23758962, 2013). "Finally, a gene signature generated with PRL-upregulated genes was associated with prolonged relapse-free survival as well as metastasis-free survival in a cohort of breast cancer patients." (PMID 23758962, 2013). "Finally, a gene signature based on PRL-upregulated genes was associated with prolonged relapse-free and metastasis-free survival in human breast cancer patients." (PMID 23758962, 2013). "However, in breast cancer cells, prolactin has also been implicated as an invasion suppressor hormone." (PMID 23853760, 2013). "Stat5 transcription factors, principal mediators of PRL effects, are frequently inactivated during metastatic progression in clinical breast cancer specimens, and loss of Stat5 signaling is associated with unfavorable prognosis and increased risk of anti-estrogen therapy failure." (PMID 23758962, 2013). "Increased risk of breast cancer has been associated with both high levels of prolactin and PHPT." (PMID 22606260, 2012). "A pooled analysis of three large prospective cohort studies reported a small increased risk for breast cancer in women with high normal or above normal levels of prolactin (>17.6 ng/mL) compared to women with below normal levels (≤9.8 ng/mL) (RR = 1.3, CI = 1.1–1.6, p-trend = 0.002)." (PMID 23227451, 2012). "However, our primary analysis of breast cancer risk according to the degree of inhibition of serotonin reuptake, a proxy for their impact on prolactin levels, was fully powered." (PMID 23227451, 2012). "In addition, studies in humans also support an association between elevated prolactin levels and the subsequent development of breast cancer." (PMID 23227451, 2012). "Ultimately, targeting metabolic pathways that are governed by PRL, which has already been implicated in the progression of breast cancer, may be of therapeutic benefit." (PMID 21294903, 2011). "Studies suggest that high circulating levels of prolactin increase breast cancer risk." (PMID 21470416, 2011). "In our model, LKB1 is associated with PRL-mediated changes in CPT1 activity in breast cancer cells." (PMID 21294903, 2011). "Atrazine causes mammary tumors in rats by affecting the hypothalamus, which affects the pituitary gland and ultimately disrupts luteinizing hormone cycling, leading to increases in endogenous estrogen and prolactin." (PMID 21622085, 2011). "Targeting metabolic pathways that are governed by PRL, which has already been implicated in the progression of breast cancer, may be of therapeutic benefit." (PMID 21294903, 2011). "Thus, we examined the relationship between single nucleotide polymorphisms (SNPs) in PRL and PRLR, serum prolactin levels and breast cancer risk in a population-based case-control study." (PMID 21470416, 2011). "Similarly, we observed increased risk related to increased levels of PRL among women with a family history of breast cancer, but women with a positive family history were relatively uncommon in this data set and results were not statistically significant." (PMID 20736944, 2010). "In conclusion, our data suggest that PRL levels may be related to several breast cancer risk factors and could potentially have value in understanding the mechanisms that mediate these factors." (PMID 20736944, 2010).
breast cancer (continued). "Selective serotonin reuptake inhibitors (SSRIs), a popular class of antidepressants, may increase breast cancer risk by stimulating the secretion of prolactin, a potential tumour promoter." (PMID 21176215, 2010). "The influence of endogenous hormones on the risk of breast cancer of women may involve in addition to estrogens effects of progesterone, prolactin, testosterone and IGF-1 on terminal differentiation of mammary stem cells." (PMID 19738607, 2009). "Sex steroids, insulin-like growth factors (IGFs) and prolactin are breast cancer risk factors but whether their effects are mediated through mammographic density, one of the strongest risk factors for breast cancer, is unknown." (PMID 19545414, 2009). "In humans, high serum prolactin levels increase the risk of breast cancer for women." (PMID 19014541, 2008). "Elevations of serum prolactin (PRL) are associated with an increased risk for breast cancer." (PMID 18254957, 2008). "The strongest associations between individual SNPs and breast cancer risk were with SNP34 (rs9466314) in "block 2" of PRL (co-dominant effect OR, 1.48; 95% CI, 1.00–2.18; p = 0.049) and SNP49 (rs34024951) in block 3 of PRLR (co-dominant effect OR, 0.85; 95% CI, 0.73–0.99; p = 0.032)." (PMID 18053149, 2007). "A recent German study of 441 cases and 552 controls reported an increase in breast cancer risk associated with genetic variation in PRL: rs1341239 (SNP35) (OR, 1.67; 95%CI, 1.11–2.50 for homozygous individuals) and rs12210179 (OR, 2.09; 95%CI, 1.23–3.52), which we did not genotype in our sample." (PMID 18053149, 2007). "Also, because administration of prolactin has been shown to cause breast cancer in animal studies, this hormone is thought to be strongly involved in the development of this malignancy." (PMID 17543123, 2007). "Prospective epidemiological studies have also shown that women with higher circulating PRL levels have an increase in risk of breast cancer, suggesting that variability in PRL may also be important in determining a woman's risk." (PMID 18053149, 2007). "Antidepressants may affect the risk of breast cancer through the influence of prolactin, of which elevated levels have been observed with use of SSRIs, tricyclic antidepressants, and other psychotropic drugs." (PMID 16523201, 2006). "It has been postulated that alcohol may influence the risk of breast cancer through effects on pituitary-prolactin secretion, metabolism and clearance of Oestrogen by the liver, or pineal-melatonin production." (PMID 12556960, 2003). "Because of the known biological activities of IGF-I, growth hormone and prolactin, and their associations with breast cancer in humans and/or animal systems, these data suggest potential biological mechanisms for the association of mammographic densities with risk of breast cancer." (PMID 12373602, 2002). "This study suggests that the effect of early first full-term pregnancy in lowering breast cancer risk may be mediated, at least in part, by permanently lowering the level of circulating prolactin." (PMID 7248160, 1981). "However, existing evidence is conflicting with its role as the drug increases prolactin levels, which might increase the risk of breast cancer." (PMID 37993971, 2023). "Therefore, in a case–control study nested in the NHS, we examined the association between circulating prolactin levels measured 10 or fewer years prior to diagnosis and risk of breast cancer by tumor expression of the PRLR, pSTAT5, and phosphorylated JAK2 (pJAK2)." (PMID 36882838, 2023). "Overall, we found that pSTAT5-positive breast cancer risk was increased for premenopausal women with high prolactin levels, suggesting that prolactin may be causally related to breast cancer risk in a subset of women through the traditional prolactin-related JAK-STAT pathway." (PMID 36882838, 2023).
breast cancer (continued). "On the basis of our observations and the recognized cooperative interactions between PRL and ER signaling in breast cancer, we hypothesized that inadequacy of the PRL/PRLR signaling axis is a major contributing cause of the poor human-in-mouse engraftment rates of ER+ PDX models." (PMID 34524841, 2021). "In addition, rabbits may be a suitable model for breast cancer types with a myoepithelial differentiation of tumor cells and a prolactin-associated tumorigenesis as well." (PMID 32824521, 2020). "In addition, CNNM2 activity was suggested previously to regulate the TRPM7 magnesium channel that is associated with breast cancer growth and metastasis, which may also provide a third model of magnesium regulation in cancer by the PRL-CNNM complex." (PMID 26969161, 2016). "Evidence from preclinical and clinical data show that elevated prolactin levels cause proliferation of breast tissue and result in breast enlargement, which may be markers for an increased risk of breast cancer development and important factors in the carcinogenicity of mammary tissue." (PMID 25713759, 2015). "However, our present analysis suggests that prolactin may also operate early in the natural history of breast cancer by increasing risk of in situ tumors, the earliest detectable breast carcinomas." (PMID 25887963, 2015). "Stat5 activation initiates cell differentiation through expression of the CDH-1-β-catenin complex, which may suggest a protective effect of PRL against neoplasm formation, because decreased Stat5a activation was associated with metastatic progression in human breast cancer." (PMID 26370564, 2015). "Furthermore, a cross-sectional study among AA pre-menopausal women found that upper body fat distribution (WHR > 0.8) was a better marker for a high risk hormonal profile (high estrogens, androgens, and prolactin, and low sex hormone binding globulin) for breast cancer than general obesity." (PMID 24118876, 2013). "PRL activates both Stat5a and Stat5b, which have 92% amino acid similarity, but are encoded by different genes and may mediate overlapping and distinct effects in breast cancer cells." (PMID 23758962, 2013). "In addition to reproductive and environmental factors, genetic variation in the prolactin (PRL) and prolactin receptor (PRLR) genes may be associated with increased prolactin levels and breast cancer risk." (PMID 21470416, 2011). "The most recent prospective study suggests that prolactin might increase the risk of breast cancer." (PMID 19738607, 2009). "Our patient experienced favorable evolution after breast cancer treatment concurrently with normalization of prolactin levels under cabergoline treatment." (PMID 40160874, 2025). "In rodents, PRL has been shown to enhance the proliferation of breast cancer cells and accelerate mammary carcinoma growth via autocrine or paracrine effects." (PMID 40478803, 2025). "Amygdalin improves breast cancer by reducing the levels of steroid hormones (E2 and PRL) and blood tumor markers (CEA, CA15.3, and CA125)." (PMID 40097629, 2025). "Experimental models show that PRL stimulates MCF-7 breast cancer cell proliferation through autocrine/paracrine activation of the JAK/STAT/cyclin D1 pathway." (PMID 41370498, 2025). "On the basis of the physiological actions of PRL, a role for this hormone in breast cancer has been suggested." (PMID 40160874, 2025). "Within breast cancer setting using different breast cancer cell models, our results importantly highlighted that PRL’s ability to regulate acinar morphogenesis and A/B polarity can be extended to HR+ positive breast cancer cells." (PMID 40157909, 2025). "Controversially, while PRL overexpression in cell culture enhances tumor growth, PRLR knockdown or antagonism can lead to more aggressive but less differentiated tumors, highlighting the context-dependent nature of PRL's role in breast cancer." (PMID 41370498, 2025).
breast cancer (continued). "Clarifying PRL/PRLR roles in breast cancer will require advanced studies, including genetically engineered models for more precise investigation." (PMID 41370498, 2025). "In summary, these results expand on the differentiation effects of PRL in mammary and breast cancer cell re-differentiation and its positive impact on patient survival outcome." (PMID 40157909, 2025). "This narrative review synthesizes compelling evidence on the antagonistic roles of PRL and melatonin in breast cancer pathogenesis and progression." (PMID 41370498, 2025). "Specifically, OCT1 interacts with the transactivation domain of STAT5A to promote prolactin-induced cyclin D1 expression, which encourages cell cycle progression in breast cancer." (PMID 40507264, 2025). "Melatonin's regulation of PRL secretion represents a critical therapeutic axis in PRL-driven breast cancers." (PMID 41370498, 2025). "Clinical correlations link elevated PRL to poorer outcomes in ER+ breast cancer, while preclinical models demonstrate melatonin's potential to synergize with chemotherapy and reduce metastasis." (PMID 41370498, 2025). "To date, all the evidence available on breast cancer and PRL-secreting PitNETs has been from retrospective analyses or case reports." (PMID 40160874, 2025). "The study found that CPD is upregulated in breast cancer through prolactin and androgen signaling, which promotes NO production." (PMID 41306918, 2025). "PRL can induce cell proliferation, tumor vascularization, and cell motility, which can promote late-stage carcinogenesis of breast cancer." (PMID 40160874, 2025). "Results revealed that DMBA-induced breast cancer caused a significant increase in biochemical parameters such as CEA, CA15.3, CA125, PRL, E2, urea, creatinine, ALT, AST, and ALP and a substantial increase in gene expression of TNF-α and BcL-2." (PMID 40097629, 2025). "Differential diagnosis requires exclusion of breast cancer, tuberculosis, sarcoidosis, and autoimmune diseases using purified protein derivative, chest imaging, prolactin testing, and ultrasound-guided core needle biopsy, which is the diagnostic gold standard." (PMID 41255485, 2025). "The strength of this review highlights the dual role of PRL in promoting breast cancer progression and melatonin's counteractive oncostatic effects through multiple mechanisms, including PRL suppression, antioxidant activity, and immune modulation." (PMID 41370498, 2025). "To further dissect the role and contribution of the PRL/PRLR pathway in regulating differentiation in breast cancer, we made use of the CRISPR/Cas9 knockout of the PRLR in MCF7 cells (MCF7/PRLR-KO) previously generated." (PMID 40157909, 2025). "Emerging evidence highlights melatonin as a potent oncostatic agent in breast cancer, countering PRL-driven oncogenesis through direct hormonal modulation, antioxidant activity, and immune regulation." (PMID 41370498, 2025). "We present a case of a 67 year-old patient with a resistant PRL-secreting PitNET who subsequently developed breast cancer." (PMID 40160874, 2025). "PRL activates the Ras-Raf-MAPK pathway in mammary tumor cell lines, which signals cell proliferation." (PMID 40160874, 2025). "As many breast cancers are responsive to prolactin concentrations, the persistent increase in prolactin of the antipsychotics has implications for public health and carcinogenesis." (PMID 39989981, 2025). "Overall, our results highlight that promoting PRL/PRLR signaling while inhibiting the YAP-CCN2 oncogenic pathway as a differentiation-based therapeutic opportunity in breast cancer with potential merit in other cancers." (PMID 40157909, 2025). "We evaluated plasma concentrations of prolactin and growth hormone measured as part of case–control studies for breast cancer nested within two large prospective cohort studies, the Nurses’ Health Studies (NHS/NHSII)." (PMID 40926263, 2025).